MTMR10 (myotubularin related protein 10)
Synonyms: FLJ20313
Tractability: PROTAC: ubiquitination databases record sites on it; its protein half-life has been measured.
Gene: Protein-coding gene on chromosome 15 (30,938,941 to 30,991,904, reverse strand). Ensembl gene ENSG00000166912.
Subcellular location (Human Protein Atlas): Nuclear bodies; Nucleoplasm; Cytosol
Pathways (Reactome):
Metabolism: Synthesis of PIPs at the early endosome membrane
Gene Ontology:
Cellular component: cytoplasm; cytosol; membrane
Genetic constraint (gnomAD): Loss-of-function variants: 51 observed, 71.91 expected, observed/expected ratio (o/e) 0.71, 90% interval 0.56 to 0.9. The upper end of that interval is the gene's LOEUF score, 0.9, which puts it in group 3 of 6, group 1 being the genes least tolerant of losing a copy. Missense variants: 835 observed, 853.32 expected, observed/expected ratio (o/e) 0.98, 90% interval 0.92 to 1.04. Synonymous variants: 361 observed, 322.36 expected, observed/expected ratio (o/e) 1.12, 90% interval 1.03 to 1.22.
Homologues: Orthologues: chimpanzee MTMR10 (99% identical), macaque MTMR10 (98% identical), mouse Mtmr10 (92% identical), dog MTMR10 (91% identical), rat Mtmr10 (91% identical), pig MTMR10 (90% identical), guinea pig MTMR10 (90% identical), rabbit MTMR10 (83% identical), tropical clawed frog mtmr10 (75% identical), zebrafish mtmr10 (62% identical), Drosophila melanogaster CG14411 (29% identical), Caenorhabditis elegans mtm-10 (20% identical), and 10 more. Paralogues in human: MTMR12 (35% identical), MTMR11 (28% identical), SBF1 (21% identical), MTMR2 (20% identical), MTMR1 (20% identical), SBF2 (20% identical), MTM1 (19% identical), MTMR3 (19% identical), MTMR4 (19% identical), MTMR9 (18% identical), MTMR8 (16% identical), MTMR6 (16% identical), and 1 more.
Diseases named in the same sentence as MTMR10 in open-access papers:
MTMR10 is named in the same sentence as 13 diseases in open-access papers, as found by Europe PMC text mining. Sharing a sentence is not in itself a finding about the gene and the disease. The quoted sentences say what the papers report.
schizophrenia (3 papers, 2016 to 2023). A major psychotic disorder characterized by abnormalities in the perception or expression of reality. "Both expressed in glial cells, MTMR10 is in a locus associated with schizophrenia and dendritic growth deficiency, substance use disorders and related behavioral traits, while SEPHS1 deregulation has been reported in rats under chronic stress." (PMID 37216417, 2023).
lung disease (1 paper, 2025). "The remaining 11 genes in the region encode proteins associated with neurologic disorders (APBA2, CHRFAM7A, MTMR10, FAN1), skin and eye pigmentation or development (OCA2, HERC2, TJP1, TRPM1), nephritis (ARHGAP11B, MTMR10, FAN1), and lung disease (ENTREP2, NSMCE3)." (PMID 40013929, 2025).
infection (2 papers, 2022). The state of being infected such as from the introduction of a foreign agent such as serum, vaccine, antigenic substance or organism. "Myotubularin-related protein 10 (MTMR10), which is associated with the protection of dendrites induced by oxidative stress or infection by pathogens and is present in several tissues was identified." (PMID 36672855, 2022).
tumor (2 papers, 2020 to 2022). "Compared with normal tissues, three genes (CYP17A1, HACD1, and MTMR10) were down-regulated in tumor tissues, while the others were up-regulated." (PMID 35295857, 2022).
genetic disorder (1 paper, 2021). "The 15q13.3 microdeletion syndrome is a genetic disorder characterized by a wide spectrum of psychiatric disorders that is caused by the deletion of a region containing 7 genes on chromosome 15 (MTMR10, FAN1, TRPM1, MIR211, KLF13, OTUD7A, and CHRNA7)." (PMID 33785025, 2021).
MTMR10 also shares sentences with these, for which no sentence is quoted: autism spectrum disorder (1 paper); epilepsy (1); Intellectual disability (1); microdeletion syndrome (1); Myotubular myopathy (1); nephritis (1); neurologic disorders (1); psychiatric disorder (1).